BDNF (brain derived neurotrophic factor)
Diseases named in the same sentence as BDNF in open-access papers (continued):
Sharing a sentence is not in itself a finding about the gene and the disease.
depression (continued). "In recent years, the increasing focus on BDNF alterations and their involvement in the onset and progression of MDD has led to growing interest, giving rise to the “neurotrophin hypothesis of depression“." (PMID 39227372, 2024). "Also, DM patients with depression, DM patients with DR, as well as T2DM patients showed lower serum levels of BDNF compared with controls." (PMID 36787304, 2023). "In the pain-depression dyad model, the AFIC-CDs groups decreased the immobile time, showed effect in increasing both the neurotransmitters’ levels and the expression of mRNA of BDNF and Tph2, and decreased the IL-1β and TNF-α levels in mouse brain cortex." (PMID 38259687, 2023). "In conclusion, from the findings in this study it is evident that BDNF plays an important role in explaining one side of the bidirectional relationship between CVD and depression; therefore, serum BDNF level could be considered as a valuable biomarker." (PMID 37895349, 2023). "Interestingly, BDNF, acting on the ventral tegmental area (VTA)–nucleus accumbens (NAc) signaling pathway, can induce a depression-like phenotype." (PMID 36973813, 2023). "Although exercise is increasingly recognised in the management of depression, acute and short-term exercise studies have failed to establish a relationship between the severity of depression and changes in peripheral BDNF." (PMID 36969600, 2023). "Bright light therapy (BLT) offers some potential in treatment-resistant depression (TRD), but its effects on BDNF levels are unknown." (PMID 37759825, 2023). "Based on this, it is not surprising that BDNF is thought to be of importance in the pathogenesis of depression." (PMID 36794673, 2023). "Currently, the major hypotheses for the development of depression include the monoamine reduction hypothesis, overactivation of the hypothalamus-pituitary-adrenal (HPA) axis, and the decrease in brain-derived neurotrophic factor (BDNF) levels." (PMID 37139495, 2023). "The influence of antipsychotic medication on BDNF levels is still not as well-known as the influence of antidepressants on depression." (PMID 36767478, 2023). "Neurogenesis regulatory proteins, such as brain-derived neurotrophic factor (BDNF), are diminished in patients with depression and could be subsequently restored by either antidepressant therapies or psychological interventions." (PMID 36969689, 2023). "The results suggested that exosomal BDNF, SERT, or synapsin from maternal serum may be a powerful tool to assess early depression and neurotoxicity as early as the first trimester." (PMID 38201206, 2023). "Therefore, the identification of the key protein that simultaneously controls both BDNF and TPH2 is important for the treatment of depression." (PMID 37914710, 2023). "Prevalence of low-BDNF values was slightly higher in subjects with depression compared to non-depressed individuals." (PMID 37012351, 2023). "In addition, the improvement in metabolic biological constants due to BDNF overexpression shows, as expected, the importance of the DRN in depression as well as the importance of this brain area in diabetes." (PMID 38067196, 2023). "Post-hoc comparisons revealed that the BDNF levels were lower in permanently depressed patients compared with those in non-depressed patients and those in patients with incident depression (p-values < 0.05), even in the adjusted model." (PMID 37895349, 2023). "In addition to BDNF, changed levels of glial cell line-derived neurotrophic factor (GDNF), vascular endothelial growth factor (VEGF), and NGF in the depression brains were reported." (PMID 37781095, 2023). "BDNF and proBDNF evening concentrations are higher in patients with alteration measured with the Athens Insomnia Scale (AIS), Pittsburg Sleep Quality Index (PSQUI) positive, and lower in those with Beck Depression Inventory (BDI) positive." (PMID 36982552, 2023).
depression (continued). "BDNF and its downstream signaling (TrkB, BDNF receptor, and CREB) participate in multiple brain repair aspects including neurogenesis, synaptic plasticity, and synaptic transmission, subsequently affecting depression development." (PMID 38273824, 2023). "Brain-derived neurotrophic factor (BDNF) is considered an essential peptide for axon growth, neuronal survival, and synaptic plasticity and has an up-regulatory role in the extracellular signal-regulated kinase (ERK) pathway in depression." (PMID 38105928, 2023). "Brain-derived neurotrophic factor (BDNF) is a neurotrophin that plays a significant role in the survival and development of neurons, being involved in several diseases such as Alzheimer’s disease and major depression disorder." (PMID 37631295, 2023). "Hesperidin decreased depression severity after 12 weeks, as compared to placebo (p = .004), but serum BDNF and cortisol were not statistically significantly different in the two groups after the intervention." (PMID 38107143, 2023). "Serum and plasma BDNF levels are lower in patients with depression than in healthy controls, indicating a negative correlation between the severity of the depression and serum BDNF." (PMID 37822121, 2023). "Schisandra extract may ameliorate the depression-like emotional state and related cognitive deficits in CUMS mice by mediating the level of BDNF in the HP." (PMID 37836833, 2023). "Furthermore, there was also a dynamic change in the expression of brain-derived neurotrophic factor (BDNF), a gene involved in the behavioral and pharmacological model of depression." (PMID 37416776, 2023). "Serotonin and dopamine release, brain-derived neurotrophic factor levels, the HPA axis, and the production of inflammatory cytokines may all be affected by disturbances in the gut microbiota during depression and anxiety." (PMID 37111321, 2023). "Lower serum mBDNF levels have been observed in patients with depression compared to healthy controls, whereas serum pro‐BDNF levels do not differ significantly." (PMID 37822121, 2023). "Furthermore, stress and depression are believed to precipitate phasic activation of the VTA–nucleus accumbens pathway, leading to DA and BDNF release in the nucleus accumbens." (PMID 38203271, 2023). "This change occurred even though brain-derived neurotrophic factor (BDNF) levels in adolescents increase with BMI, demonstrating that the impacts of T2DM on the brain are far worse than those typically observed in depression alone." (PMID 37664841, 2023). "Prevalence of low-BDNF values was higher in participants with depression, as compared to non-depressed subjects (14.9 vs. 9%; P = 0.06)." (PMID 37012351, 2023). "OSAS patients with depression have lower levels of BDNF and pro-BDNF compared with OSAS patients with no mood disturbances." (PMID 36982552, 2023). "Accordingly, soldiers from Afghanistan with PTSD together with depression symptoms presented lower plasmatic BDNF levels compared to non-PTSD soldiers." (PMID 36901924, 2023). "It increases hormones levels such as serotonin and the serum concentration of the brain-derived neurotrophic factor, thus, reducing depression and improving sleep without any change in oxidative stress." (PMID 37422660, 2023). "Additionally, brain-derived neurotrophic factor (BDNF), a “master-regulator” molecule with key roles in promoting neuroplasticity, expression is significantly reduced in patients with depression." (PMID 37719598, 2023). "Indeed, type-2-diabetes-induced depression was accompanied by an increase in pro-inflammatory cytokines, including TNF-α, and a reduction in the BDNF content in the hippocampus." (PMID 37892186, 2023).
depression (continued). "Synaptic density is decreased in patients with depression, detected by positron emission tomography (PET), while BDNF induces dendritic arborization and neurogenesis, which underlies reversal of depressive behavior in animal models after 1-month of SSRIs or tricyclic antidepressants." (PMID 36911109, 2023). "Since the data of BDNF, cortisol and other depression-related biomarkers were not sufficient to perform a valid meta-analysis, the results from each included study were summarized here." (PMID 37386630, 2023). "The serum levels of BDNF, NT-3, and 5-HT in the depression group were higher than those of the non-depressed group and the control group, and the serum levels of NT-3 in the non-depression group were more remarkable than that of the control group (P < 0.05)." (PMID 37750080, 2023). "We hasten to add that BDNF is not the only component in the functioning of dopamine and serotonin systems to be involved in aggression, depression, and suicide, and psychiatric disorders." (PMID 39484176, 2023). "A previous report demonstrated that responders to treatment (≥50% improvement in depression ratings) had higher pre-treatment BDNF levels than did non-responders." (PMID 36831119, 2023). "This compound is an antioxidant naphthodianthrone which is also probably responsible for the increased hippocampal brain-derived neurotrophic factor (BDNF) concentration induced by H. triquetrifolium administration, thus reverting the depression and stress-induced cognitive deficit." (PMID 37627598, 2023). "In particular, under regulatory control by miRNA-146a-5p, tropomyosin receptor kinase B (NTRK2), as the preferred receptor of brain-derived neurotrophic factor (BDNF), plays a key role in the neurotrophic hypothesis of depression." (PMID 36426595, 2023). "Diosgenin, one of the primary bioactive compounds found in fenugreek seeds, shows promise in rectifying gut microbiota imbalances, regulating HPA axis secretion levels, upregulating hippocampal BDNF signaling pathway expression, promoting AHN, and treating depression." (PMID 38152691, 2023). "In conclusion, A. muciniphila may play a critical role in mood regulation and depression prevention by affecting the MGBA, regulating inflammation, producing SCFAs, and modulating BDNF levels." (PMID 37492530, 2023). "BDNF might mediate some of those changes, contributing to the overall decline in cognitive functions and psychiatric OSA sequelae, such as depression." (PMID 36768132, 2023). "Controlling for anxiety (BAI) and depression (BDI-II), levels of glutamate (F = 20.178, p < 0.001, η2p = 0.419), BDNF (F = 9.784, p < 0.004, η2p = 0.259) and dopamine (F = 19.134, p < 0.001, η2p = 0.406) were significantly lower in patients with FMD than in CTR." (PMID 37330537, 2023). "Indeed, we showed here that the expression of neurotrophic factors, such as BDNF, NGF, and FGF-2, which are negatively affected in the pathogenesis of depressive disorders, can be enhanced by short-term treatment with irisin." (PMID 37298063, 2023). "BDNF-mediated signaling along with vascular endothelial growth factor (VEGF) and insulin-like growth factor 1 (IGF-1) subsequently give rise to the repair of neuro-structural abnormalities in patients with depressive disorders." (PMID 37242525, 2023). "The same inverse relationship could be interpreted from mir-132 and BDNF relations in addition to mir-16 and SERT in depression disorder." (PMID 37396946, 2023). "The Revised Fibromyalgia Impact Questionnaire (FIQR), Short-Form Health Survey (SF-12), pain visualized analog scale (pain VAS), Beck Depression Inventory-II (BDI-II), polysymptomatic distress scale (PSD) and serum BDNF were measured and compared at baseline and 4 weeks after treatment in FM group." (PMID 35501732, 2022).
depression (continued). "CUMS exposure also significantly decreased GSH, BDNF, phosphorylation of AKT, and mTOR in PFC, and antioxidant drugs such as resveratrol, 5-HT, or carvedilol can increase BDNF, AKT, and mTOR and decrease oxidative stress, significantly alleviating depression." (PMID 35663199, 2022). "Therefore, low serum BDNF is related to both neurodegenerative diseases (NDD) such as Huntington’s, Parkinson’s, and Alzheimer’s diseases, depression and metabolic disorders such as diabetes, obesity, dyslipidemia, inflammation and hypertension." (PMID 36185667, 2022). "The main finding of the meta-analysis was a negative correlation between circulating levels of BDNF and depression severity score (standardized mean difference = −0.22, Confidence Interval 95% = −0.38, −0.05, p = 0.01)." (PMID 35740389, 2022). "Nevertheless, none of the examined SNPs were found to be associated with depression in colorectal cancer patients, including the deletion SNP of 5-HTTLPR, rs6295 in serotonin 1a receptor (HTR1a), rs6265 in BDNF, rs1360780 in FKBP5 and rs4680 in COMT." (PMID 35528795, 2022). "According to the neurotrophic hypothesis, another pathophysiological hypothesis of depression, the downregulation of neurotrophins like brain-derived neurotrophic factor (BDNF) is related to persistent stress and depression." (PMID 36506414, 2022). "Finally, treating Thy1-C/EBPβ Tg mice with the anti-inflammatory drug aspirin, AAV-BDNF or BDNF mimetic compound 7,8-DHF reduced HFD-induced depression-like behaviors, indicating their protective effects." (PMID 36578534, 2022). "Neurogenesis is governed by substances like BDNF, which is absent in patients with major depression." (PMID 36311022, 2022). "In addition to the hippocampus, the BDNF system in other brain regions such as the prefrontal cortex (PFC) and nucleus accumbens (NAc) has also been demonstrated to correlate with depression." (PMID 35959431, 2022). "Only one article associated the number of depressive episodes with inflammatory factors (IL-6), but not with BDNF or with the presence of previous episodes of depression." (PMID 35740389, 2022). "Another study of depression in adolescent patients discovered increased BDNF but no changes in NGF or GDNF." (PMID 35431783, 2022). "Specifically, we hypothesize the biological indicators expression of reactive depression may differ from that of endogenous depression in depression-related biological mechanisms including classic HPA-axis, BDNF, DA, and novel inflammatory-immune." (PMID 35295780, 2022). "Regarding the effect of antidepressants on BDNF in depression, elevated levels of BDNF in the hippocampus were found in patients with depression treated with antidepressants compared to non-treated patients." (PMID 35563389, 2022). "The present study aimed to analyze the effects of augmented MBCT along with standard treatment dominated by pharmacotherapy on psychological state, compliance, brain-derived neurotrophic factor (BDNF), and nerve growth factor (NGF) expression levels in patients with depression." (PMID 35069013, 2022). "Those with a comorbid diagnosis of cocaine addiction and depression, irrespective of being primary or induced, show lower BDNF levels." (PMID 35370811, 2022). "Decreased brain-derived neurotrophic factor (BDNF) in the hippocampus and PFC of mice exposed to chronic unpredictable stress was reversed by the administration of ciproxifan (H3R antagonist/inverse agonist) in preclinical depression models." (PMID 36430254, 2022). "A leading hypothesis for the pathogenesis of depression is that CREB and BDNF play an important role in adaptation of the hippocampus to chronic stress and antidepressants." (PMID 35338110, 2022). "Aerobic exercise could relieve depression symptoms, promote neurogenesis, and increase the ratio of BDNF/proBDNF in the ischemic hippocampus of PSD rats." (PMID 35370607, 2022).
depression (continued). "To confirm that C/EBPβ promotes HFD-induced depression via downregulating its downstream factor BDNF, we directly injected AAV-BDNF or AAV-GFP into the hippocampus of WT or Thy1-C/EBPβ Tg male mice fed an HFD for 8 weeks and continued the diet for another 4 weeks." (PMID 36578534, 2022). "In the chronic social defeat stress (CSDS)-induced depression mice model, metformin alleviates depression-like behavior, improves CSDS-induced synaptic defects, and upregulates brain-derived neurotrophic factor (BDNF) expression by activating AMPK/CREB signaling pathways." (PMID 35955427, 2022). "Peripheral BDNF levels are decreased in patients with depression compared with non-depressed participants as well as BDNF mRNA levels in distinct cortical areas." (PMID 35203890, 2022). "As a mechanistic molecule, brain-derived neurotrophic factor (BDNF) can modulate neurogenesis, reflecting the neuroplasticity hypothesis of stress-induced depression." (PMID 36014820, 2022). "Patients with depression had significantly lower levels of BDNF than the participant in the non-depressed group (SMD [95%CI] = − 0.60 [− 1.10 to − 0.10], p-value < 0.001, I2 = 88%, p-value < 0.001)." (PMID 35287688, 2022). "A study in a chronic mild stress-based animal model of depression showed impairment of glutamate/GABA presynaptic release, brain-derived neurotrophic factor (BDNF) mRNA trafficking in dendrites, and reduced length of apical dendrites in CA3 pyramidal neurons of the hippocampus." (PMID 36499675, 2022). "A recent study proposed that the anthocyanin extract from blueberries ameliorates depression-like behavior in CUMS by upregulating monoamine neurotransmitter levels and BDNF expression and inhibiting MAOA, which promotes neurogenesis via the ERK/CREB/BDNF signaling pathways." (PMID 36499295, 2022). "Our results demonstrate that repeated rapastinel injection could alleviate depression-like behaviors similar with ketamine binding to NMDAR, which further activated the VGF/BDNF/TrkB/ERK pathway, thereby regulating protein translation (e.g., VGF and BDNF)." (PMID 36550125, 2022). "Meta-analysis indicated that circulating BDNF levels showed a significant negative correlation with the severity of depression (SMD = −0.24, 95% CI = −0.37, −0.10, p = 0.01, k = 5, n = 271)." (PMID 35740389, 2022). "There is growing evidence that modulation of BDNF expression levels can exert antidepressant effects, where BDNF-cAMP response element binding protein (CREB) signaling is one of the most attractive signaling pathways for the treatment of depression." (PMID 36440427, 2022). "This suggests that compounds capable of stimulating the production of endogenous BDNF or the activation of TrkB-receptors in the PFC and hippocampus may be potentially useful for the treatment or prevention of depression and AD via protection of astrocytes." (PMID 35563389, 2022). "Thus, the aim of our study was to investigate serum BDNF and CRH levels in vitiligo patients and healthy controls in relation to the observed symptoms of depression and anxiety disorders." (PMID 35508633, 2022). "However, when combined with anxiety and depression, the secreted BDNF in the ACC, including the hippocampus to maintain the homeostasis of BDNF in the brain." (PMID 35401106, 2022). "BDNF levels were lower in the patients with depression compared to non-depressed subjects (SMD [95%CI] = − 0.60 [− 1.10 to − 0.10])." (PMID 35287688, 2022). "The decreased concentrations of BDNF, glial cell line-derived neurotrophic factor (GDNF), Artemin (ARTN), nerve growth factor (NGF), and vascular endothelial growth factor (VEGF) are a good repetitive finding in depression." (PMID 35369081, 2022). "Thus, MYR relieved depression and anxiety through regulation of the HPA axis, neurotransmitters in the brain fear circuit regions, and the BDNF-ERK signaling pathway." (PMID 35722162, 2022).